GOLGA8R (golgin A8 family member R)
Tractability: No criterion of Open Targets' tractability assessment is met for any kind of drug.
Gene: Protein-coding gene on chromosome 15 (30,400,562 to 30,414,260, reverse strand). Ensembl gene ENSG00000186399.
Pathways (Reactome):
Signal Transduction: CDC42 GTPase cycle; RHOD GTPase cycle
Gene Ontology:
Biological process: Golgi organization
Cellular component: cis-Golgi network; Golgi cis cisterna; Golgi cisterna membrane; Golgi apparatus
Genetic constraint (gnomAD): Loss-of-function variants: 6 observed, 3.53 expected, observed/expected ratio (o/e) 1.7, 90% interval 0.82 to 1.95. That is too few expected variants to judge how well the gene tolerates losing a copy. Missense variants: 38 observed, 21.43 expected, observed/expected ratio (o/e) 1.77, 90% interval 1.33 to 1.97. Synonymous variants: 8 observed, 6.33 expected, observed/expected ratio (o/e) 1.26, 90% interval 0.72 to 1.88.
Homologues: Orthologues: chimpanzee GOLGA8S (89% identical), mouse Golga2 (43% identical), dog GOLGA2 (43% identical), tropical clawed frog golga2 (33% identical), zebrafish golga2 (30% identical), Drosophila melanogaster GM130 (21% identical), Caenorhabditis elegans golg-2 (19% identical), rat Golga2l1 (5% identical). Paralogues in human: GOLGA8N (99% identical), GOLGA8O (99% identical), GOLGA8Q (98% identical), GOLGA8M (92% identical), GOLGA8H (90% identical), GOLGA8J (90% identical), GOLGA8K (89% identical), GOLGA8T (89% identical), GOLGA8S (83% identical), GOLGA8F (79% identical), GOLGA8G (79% identical), GOLGA8A (65% identical), and 6 more.